BCL7B (BAF chromatin remodeling complex subunit BCL7B)
Diseases named in the same sentence as BCL7B in open-access papers (continued):
Sharing a sentence is not in itself a finding about the gene and the disease.
tumor (4 papers, 2015 to 2022). "A more in-depth research based on tumor samples revealed that the BCL7B gene expression has different degrees of correlation with infiltrating immune cell subsets in a multiple tumor environment." (PMID 35910232, 2022). "To further verify the protein expression of BCL7B gene in 33 tumor tissues and corresponding normal tissues, and to make our results more convincing, we explored the immunohistochemical staining of BCL7B in the HPA database." (PMID 35910232, 2022). "We first assessed the expression of BCL7B gene in 40 normal and tumor tissues from TCGA dataset and found that its expression was higher in eight tumors, including BRCA, CHOL, ESCA, GBM, HNSC, KIRC, KIRP, and LIHC." (PMID 35910232, 2022). "The correlation between the immune infiltration level and expression level (TPM) of BCL7B was analyzed by Spearman’s correlation in 39 kinds of tumor environment." (PMID 35910232, 2022). "Previous studies showed that the BCL7B gene regulates the apoptotic and Wnt signaling pathways, which involve in tumor suppression." (PMID 35910232, 2022). "The Wilcoxon rank sum test and Kruskal–Wallis test were used to compare the expression of BCL7B gene in tumor tissues with different clinicopathological features." (PMID 35910232, 2022). "So, we further performed Spearman’s rank correlation coefficient analysis to assess the association between BCL7B gene expression and PFI of tumor patients." (PMID 35910232, 2022). "Cell counting kit-8 (CCK-8) and transwell tests can be used to detect the proliferation and invasion of tumor cells in BCL7B high and low expression groups." (PMID 35910232, 2022). "These analyses contribute to elucidate the role of BCL7B in tumor diagnosis, prognosis, and tumorigenic mechanism." (PMID 35910232, 2022). "Our result reflected that BCL7B had different degrees of correlation with 47 immune checkpoints in tumor microenvironment." (PMID 35910232, 2022). "We showed that a combination of PODXL with ITGB1 and a combination of BCL7B with ITGB1 predicted the postoperative outcomes of PDAC patients better than tumor size and the TNM staging system." (PMID 31166991, 2019). "In conclusion, the combination of PODXL with ITGB1 and the combination of BCL7B with ITGB1 accurately predicted the postoperative prognosis of PDAC patients better than tumor size and the UICC TNM stage." (PMID 31166991, 2019). "BCL7B, located on chromosome 7, is a member of the BCL7 family of genes and is thought to be a tumor-associated gene." (PMID 25569233, 2015). "Collectively, these findings suggest that BCL7B is a novel tumor suppressor gene and is required for the terminal cell differentiation." (PMID 25569233, 2015). "Above all, the findings indicated that BCL7B expression could be used as a predictor of tumor prognosis." (PMID 35910232, 2022). "Also, we explored the potential signaling pathways that BCL7B gene participates in tumorigenesis, development, and tumor microenvironment." (PMID 35910232, 2022). "GSEA was conducted to explore the top five GSEA terms through which BCL7B may involve in 33 tumor types from TCGA." (PMID 35910232, 2022). "However, there are some differences between BCL7B and other tumor suppressors." (PMID 25569233, 2015). "We found that the BCL7B gene expression was positively correlated with the six types of infiltrating immune cells in BLCA, which conformed to the strong correlation between tumor immune infiltration and BLCA." (PMID 35910232, 2022). "In the present study, we investigated the use of PODXL, BCL7B, ARHGEF4, and ITGB1 as useful markers for the prognosis of postoperative PDAC patients in comparison with tumor size and the TNM staging system." (PMID 31166991, 2019). "We investigated the abilities of PODXL, BCL7B, ARHGEF4, and ITGB1 to predict prognosis in PDAC in comparison with UICC TNM stage and tumor size." (PMID 31166991, 2019). "PODXL, BCL7B, ARHGEF4, ITGB1, or tumor size were not included in the final model of the multivariate analysis." (PMID 31166991, 2019).
BCL7B also shares sentences with these, for which no sentence is quoted: oral squamous cell carcinoma (2 papers); rectum adenocarcinoma (2); skin cutaneous melanoma (2); thyroid carcinoma (2); uveal melanoma (2); B-cell non-Hodgkin lymphoma (1); bladder urothelial carcinoma (1); Breast invasive carcinoma (1); cervical squamous cell carcinoma (1); cholangiocarcinoma (1); colon adenocarcinoma (1); Crohn disease (1); diffused large B-cell lymphoma (1); endocervical adenocarcinoma (1); esophageal carcinoma (1); esophageal squamous cell carcinoma (1); genetic disorder (1); head and neck squamous cell carcinoma (1); lung adenocarcinoma (1); lung squamous cell carcinoma (1); lymphoid neoplasm (1); medulloblastoma (1); mesothelioma (1); ovarian serous cystadenocarcinoma (1); pancreatic adenocarcinoma (1); paraganglioma (1); pheochromocytoma (1); prostate adenocarcinoma (1); psoriatic arthritis (1); stomach cancer (1).
A further 5 diseases each share a sentence with BCL7B in 1 paper.